C11orf96 (chromosome 11 open reading frame 96)
Synonyms: AG2
Gene: Protein-coding gene on chromosome 11 (43,942,637 to 43,943,878, forward strand). Ensembl gene ENSG00000187479.
Subcellular location: Cytoplasm
Subcellular location (Human Protein Atlas): Cytosol; Nucleoplasm; Focal adhesion sites
Genetic constraint (gnomAD): Loss-of-function variants: 6 observed, 3.4 expected, observed/expected ratio (o/e) 1.76, 90% interval 0.83 to 1.95. That is too few expected variants to judge how well the gene tolerates losing a copy. Missense variants: 149 observed, 115.17 expected, observed/expected ratio (o/e) 1.29, 90% interval 1.13 to 1.48. Synonymous variants: 72 observed, 53.53 expected, observed/expected ratio (o/e) 1.34, 90% interval 1.11 to 1.64.
Homologues: Orthologues: macaque C14H11orf96 (99% identical), mouse Gm13889 (96% identical), guinea pig C11orf96 (93% identical), rabbit C11orf96 (89% identical), tropical clawed frog c4h11orf96 (70% identical), rat C3h11orf96 (68% identical), zebrafish C25H11orf96 (56% identical).
Diseases named in the same sentence as C11orf96 in open-access papers:
C11orf96 is named in the same sentence as 8 diseases in open-access papers, as found by Europe PMC text mining. Sharing a sentence is not in itself a finding about the gene and the disease. The quoted sentences say what the papers report.
viral infection (2 papers, 2022 to 2023). "The gene C11orf96 encodes a protein of unknown function but which has been reported to be upregulated after viral infection." (PMID 37478057, 2023). "In the present study, we successfully identified a host protein C11orf96 that was significantly upregulated after viral infection." (PMID 35538492, 2022). "As observed earlier, the expression level of C11orf96 was significantly upregulated after viral infection, indicating that this protein is involved in regulating the life cycle of the virus." (PMID 35538492, 2022). "Therefore, understanding the biological characteristics of the C11orf96 protein is critical to study its biological functions in viral infections." (PMID 35538492, 2022). "C11orf96 is a protein that is significantly upregulated after virus infection." (PMID 35538492, 2022).
colorectal cancer (1 paper, 2020). A primary or metastatic malignant neoplasm that affects the colon or rectum. "C11orf96 is an open reading frame, considered as a potential prognostic marker in colorectal cancer." (PMID 33473258, 2020).
oral squamous cell carcinoma (1 paper, 2024). "Impressively, lysates obtained from oral squamous cell carcinoma lines HSC2 and TR146 but also the healthy equivalent, the oral epithelial cells, all provoked the increased expression of STC1, AREG, and C11orf96 in gingival fibroblasts." (PMID 39061769, 2024).
Pancytopenia (1 paper, 2017). An abnormal reduction in numbers of all blood cell types (red blood cells, white blood cells, and platelets). "Most of the genes from day 1 appeared 2-fold downregulated (e.g., CDCA7L or GBP2), but three were 3–5-fold upregulated (C11orf96, GLUL, TM4SF19) relative to H0 when developing a HARS without pancytopenia." (PMID 28236054, 2017).
tumor (4 papers, 2020 to 2025). "Our results showed that the relative mRNA expression of ADIRF, MT2A, MT1M, and JUNB was downregulated after TGF-beta treatment and/or tumor stimulation, while the expression level of C11orf96 was upregulated, even after tumor stimulation." (PMID 33777046, 2021). "Some genes, such as MT2A, NEAT1, ATP1B1, and C11orf96, were highly expressed in tumour cells from ccRCC1." (PMID 34168986, 2021). "Genes with higher expression in the Normal tissue adjacent to neoplasm group included these markers as well as TAGLN and C11orf96." (PMID 40616092, 2025). "In the TCGA_LIHC cohort, 16 of 120 genes were downregulated in HCC tissue rather than in adjacent non-tumor tissue, and 9 of 16 genes, namely, ALDH8A1, C11orf96, CLYBL, EFNB3, ENG, NPC1L1, PIM3, SEC14L2, and SLC8A1, displayed a significant difference (p < 0.05)." (PMID 33352935, 2020).
C11orf96 also shares sentences with these, for which no sentence is quoted: cancer (2 papers); adenoma (1); clear cell renal cell carcinoma (1).